APP (amyloid beta precursor protein)
Diseases named in the same sentence as APP in open-access papers (continued):
Sharing a sentence is not in itself a finding about the gene and the disease.
Alzheimer disease (continued). "Then, APP/PS1 transgenic mice model experiments were conducted to explore the effect of acorn polyphenols on Alzheimer’s disease and to provide a reference for the development of acorn polyphenol resources and drug development in Alzheimer’s disease." (PMID 39408864, 2024). "Amyloid precursor protein (APP) is a brain-rich, single pass transmembrane protein that is proteolytically processed into multiple products, including amyloid-beta (Aβ), a major driver of Alzheimer disease (AD)." (PMID 38318375, 2024). "In 7-month-aged APP/PS1 mice with memory deficit, treatment with the polysaccharide fraction of A. membranaceous significantly improved the cognitive ability of APP/PS1 mice, lessened apoptosis and the accumulation of Aβ, which is highly characteristic in patients with Alzheimer’s disease (AD)." (PMID 39199238, 2024). "Furthermore, we emphasize the clinical relevance by evaluating erinacines in a metabolically stressed APP/PS1 mouse model, which more accurately reflects the complexities of human Alzheimer's disease (AD), where metabolic syndrome is a common comorbidity." (PMID 39690860, 2024). "BACE1 is involved in two different pathways that produce amyloid-beta through reverse cholesterol transport, and its role in APP cleavage offers potential to treat Alzheimer’s disease early on rather than treating the disease later in its progression." (PMID 37444065, 2023). "In the mouse model of Alzheimer’s disease (AD), the double transgenic mouse model APP/PS-1, the treatment of 7-month-old but not 12-month-old mice with ANDRO for one month significantly decreased the Amyloid-β (Aβ) aggregates." (PMID 36674622, 2023). "With FRA10AC1 being well-connected by three binary interactors, namely VPS29, GATD3A, and EEF1D, to APP (amyloid β A4 precursor protein), the previously reported information characterizing two FRA10AC1 SNPs biomarkers of Alzheimer’s disease is further supported." (PMID 36980839, 2023). "Additionally, upregulation of the amyloid precursor protein (APP), known to be involved in Alzheimer’s disease, and of the OLIG1 and OLIG2 transcription factors was found, supporting the idea of deficits in neurogenesis and neuronal differentiation." (PMID 36831205, 2023). "The demethylated derivative of sterubin, eriodictyol, found in the peel of citrus fruits and some Chinese herbal medicines, also showed an anti-Alzheimer’s-disease effect through antiferroptotic activity in vitro in HT22 cells and in vivo in the APP/PS1 mouse model of Alzheimer’s disease." (PMID 36677534, 2023). "Apolipoprotein (apo) E4, being a major genetic risk factor for Alzheimer’s disease (AD), is actively involved in the proteolytic processing of amyloid precursor protein (APP) to amyloid β (Aβ) peptide, the principle constituent of amyloid plaques in Alzheimer Disease (AD) patients." (PMID 38204816, 2023). "The amyloid precursor protein (APP) has a crucial role in the pathology of Alzheimer's disease, but its functions in the brain are still not clear." (PMID 37740826, 2023). "Interestingly, CDNF has been shown to improve long-term memory in both WT mice and APP/PS1 mice, modeling Alzheimer’s disease." (PMID 37555005, 2023). "In this study we compared cases of EOAD (without known causal mutations in APP, PSEN1 or PSEN2), Alzheimer’s disease in individuals who had DS (AD-DS), and healthy ageing disomic individuals." (PMID 37580797, 2023). "These transgenic mice do not have human amyloid precursor protein (APP) nor do they generate human Aβ, and therefore, lack amyloid toxicity, which is thought to be the main pathological hallmark of Alzheimer’s disease." (PMID 35216391, 2022). "In a mouse model of Alzheimer's disease, intra‐cranial delivery of anti‐ASC Abs prevented the ASC speck‐induced aggregation of Aβ in the hippocampus of APP/PS1 mice injected with Aβ seeds from APP/PS1 brain lysates." (PMID 35438238, 2022).
Alzheimer disease (continued). "Moreover, APP increased AQP1 expression in brains from patients with Alzheimer’s disease through an epigenetic mechanism and AQP1 overexpression reduced Aß production arising from APP cleavage by inhibiting the binding between ß-secretase (BACE1) and APP." (PMID 36077012, 2022). "In Alzheimer’s disease-like conditions, OL loss was also most severe in the CA3 and CA4 of APP/PS1 mice, although the disease did not impair the rate of OPC differentiation into OLs in those regions." (PMID 35465615, 2022). "While differential modulation of APP processing and Aβ transcytosis by PICALM has been reported, significant effects of PICALM modulation of tau pathology progression have also been evidenced in Alzheimer’s disease models." (PMID 36552756, 2022). "Interestingly, MBG also downregulated the genes involved in the Alzheimer’s disease (AD) genomic profile in DSS rats, i.e., APP mRNA expression was almost two times lower, and PSEN-1 mRNA was 40% lower in DSS-MBG vs. DSS-LS rats." (PMID 35562955, 2022). "Similarly, stimulating social contact has been presented as a neurogenic trigger in APP/PS1 mice, an established model for Alzheimer’s disease with progressive spatial memory failure." (PMID 36407114, 2022). "It is also necessary to study the hypoxanthine-guanine phosphoribosyltransferase (HGprt) enzyme, AT, and APP using expression vectors for exploring their impact on LND, thrombosis as well as other human diseases, especially the ones related to APP such as Alzheimer's disease (AD) and cancer." (PMID 35860682, 2022). "In the last several decades, traditional transgenic mouse models of Alzheimer's disease (AD), such as APP/PSEN1 and 5xFAD, overexpress human mutant amyloid precursor protein (APP) to increase pathological amyloid-β peptide and were widely used in research to develop therapeutic approaches for AD." (PMID 35966019, 2022). "Moreover, we have found recently that despite a deficit of sleep SWRs the APP/PS1 mice, a model of Alzheimer’s disease, show undisturbed spatial reference memory." (PMID 34711860, 2021). "Interaction between APP and CD74 reduces the production of beta amyloid in Alzheimer’s disease." (PMID 34685653, 2021). "It has been proposed that strategies aimed at the prevention of amyloid precursor protein (APP) palmitoylation through the development of specific inhibitors could prevent and/or treat Alzheimer's disease." (PMID 34343464, 2021). "For example, icariin exerts neuroprotective effects via modulating the CD4+ T lymphocyte-related immunoinflammatory responses in APP/PS1 mice and may be a promising drug against Alzheimer’s disease progression." (PMID 33714945, 2021). "In Alzheimer’s disease, GPCR is involved as a modulator of amyloid-beta generation through the modulation of α-, β-, and γ-secretases in the proteolysis of amyloid precursor protein (APP)." (PMID 34199148, 2021). "These NPs could enter the cells to inhibit the overexpression of human amyloid precursor protein (APP) and β-amyloid (Aβ), which are among the main factors responsible for Alzheimer’s disease." (PMID 34769212, 2021). "In this regard, in APP/PS1 transgenic mice, a model of Alzheimer’s disease, chronic treatment with ciproxifan reduced both COX-1 and COX-2 activities, decreased the level of pro-inflammatory cytokines IL-1α, IL-1β, and IL-6, and increased the level of anti-inflammatory cytokine TGF-1β." (PMID 33918940, 2021). "In APP/PS1 transgenic mice, the animal model of Alzheimer’s disease, systemic administration of s-EV derived from hypoxia-preconditioned MSCs reduced cognitive impairment in part by decreasing brain inflammation through the inhibition of astrocytes and microglia activation." (PMID 33462263, 2021). "ADAM10 is the main α-secretase that participates in the non-amyloidogenic cleavage of amyloid precursor protein (APP) in neurons, inhibiting the production of β-amyloid peptide (Aβ) in Alzheimer’s disease (AD)." (PMID 33670873, 2021).
Alzheimer disease (continued). "This pattern has also been observed in a mouse model for Alzheimer’s disease (AD), where ILK protein levels are significantly decreased in the hippocampus of APP/PS1 mice, which display perturbed neurogenesis and memory deficits, and can be rescued by overexpressing ILK." (PMID 34393704, 2021). "Interestingly, amyloid precursor protein (APP), which is found in Alzheimer’s disease patients, can reduce Cu (II) to Cu(I) in a cell-free system; moreover, Cu (II) can be reduced to Cu(I) and remains bound to APP." (PMID 32328835, 2020). "A decrease in the abundance of Allobaculum has been observed in the APP/PS1 mouse model of Alzheimer’s disease and absent in restrained mice as a depression-like animal model, while high in the control group." (PMID 33195226, 2020). "ADAM9 has been demonstrated to be involved in neurodegenerative disease by regulating the cleavage of amyloid precursor protein (APP), which might be relevant in Alzheimer’s disease." (PMID 33096780, 2020). "Rh2 can also prevent Alzheimer’s disease symptoms by promoting nonamyloidogenic cleavage of amyloid precursor protein (APP) via a cholesterol and lipid raft-dependent pathway." (PMID 33041822, 2020). "In the case of Alzheimer’s disease (AD), genetically engineered mice expressing the mutant genes for both APP and PSEN1 (here collectively termed APP/PS1 mice) yielded valuable insights into the mechanisms and consequences of amyloid deposition in the intact brain." (PMID 32178700, 2020). "APP, COX-2 and PARP are well-known inflammatory biomarkers for Alzheimer’s disease." (PMID 33167585, 2020). "For example, the activation of Wnt signaling pathway reportedly enhances the cognitive function of adult mice and rescues memory deficit in APP/PS1-transgenic mice, an Alzheimer’s disease model, whereas blockade of Wnt signaling reduces hippocampal neurogenesis." (PMID 32397562, 2020). "This mutation, which was found in a Japanese pedigree of familial Alzheimer’s disease, is the deletion of codon 693 of APP gene, resulting in mutant Aβ lacking the 22nd glutamate." (PMID 32093100, 2020). "In elderly people without Alzheimer’s disease, APP is preferentially processed by α-secretase prior to the cleavage by γ-secretase." (PMID 33370284, 2020). "It was also reported that OPP at concentration of 300 μL/10 mL have lowered the APP levels in FAD cells to a level expressed in the WT control sample, reflecting the ability of OPP to reduce the APP levels on individuals without Alzheimer’s disease." (PMID 33167585, 2020). "The link between cholesterol homeostasis and cleavage of the amyloid precursor protein (APP), and how this relationship relates to Alzheimer's disease (AD) pathogenesis, is still unknown." (PMID 32865299, 2020). "Recently, it has been possible to confirm the obligatory role of APP in the clinical, biochemical, and neuropathological findings of Alzheimer‐like disease studying a case of PT21 with DS and without Alzheimer disease, lacking the APP duplication." (PMID 31237416, 2019). "In addition to Notch receptors, the γ-secretase complex cleaves at least 90 other substrates, including the amyloid precursor protein (APP), which accumulates abnormally in Alzheimer's disease." (PMID 30890522, 2019). "In the context of Alzheimer’s disease, lentivirus vectors have been applied for RNA silencing to knock down BACE1 attenuated amyloid precursor protein (APP) cleavage and β-amyloid production, resulting in reduced neurodegeneration and behavioral deficits in an Alzheimer’s disease mouse model." (PMID 29883422, 2018). "Iron response proteins (IRP1 and IRP2) increase amyloid precursor protein (APP) expression, which is the precursor to amyloid-β in Alzheimer’s disease, as well as the expression of α-synuclein, which is a critical component of the Lewy bodies in Parkinson’s disease." (PMID 30360386, 2018).
Alzheimer disease (continued). "Finally, we evaluated the beneficial effect of TAT‐CAONi in APP/PS1 mice, a mice model widely used in Alzheimer's disease studies." (PMID 29577585, 2018). "In the present study, we have used murine neuroblastoma N2a cells stably transfected with human amyloid precursor protein (APP) to assess whether and how Xn affects molecular mechanisms relevant to Alzheimer’s disease (AD)." (PMID 29670521, 2018). "Higher levels of the Col6a1 transcript and protein were observed in hippocampal neurons of mice expressing mutant human APP, and a higher expression of COL6A1, COL6A2 and COL6A3 mRNA was also detected in the dentate gyrus of Alzheimer's disease patients compared with cognitively normal controls." (PMID 29728408, 2018). "It is generally accepted that increased amyloidogenic processing of the amyloid precursor protein (APP), compromised amyloid beta (Abeta) degradation, and post-translational modifications of Abeta peptides contribute to the pathogenesis of Alzheimer’s disease (AD)." (PMID 29673150, 2018). "The remaining open questions are whether APP regulates GDNF expression in different types of neurons within the CNS and whether GDNF participates in Alzheimer’s disease." (PMID 28878618, 2017). "Amyloid precursor protein (APP) and APP-like protein, well known in the pathogenesis of Alzheimer’s disease, participate in nAChR clustering via the Lrp4-MuSK signal in cooperation with agrin-mediated signal and also contribute to the presynaptic differentiation of the neuromuscular junction." (PMID 28441759, 2017). "The amyloid precursor protein (APP) can be processed to generate the amyloid β (Aβ) peptides, which aggregate to form senile plaques, one of the major pathological hallmarks found in Alzheimer’s disease (AD; Masters and Selkoe, 2012)." (PMID 28424586, 2017). "Many key proteins involved in disease progression are N-glycosylated, such as amyloid precursor protein (APP) and β-site amyloid precursor protein-cleaving enzyme 1 (BACE-1) in Alzheimer's disease (AD) and alpha-fetoprotein (a clinical biomarker) in hepatocellular carcinoma." (PMID 27259237, 2016). "In Alzheimer’s disease ADAM-10 could have beneficial properties, as APP processing by ADAM-10 reduces both APP cleavage by BACE1 and β-amyloid generation, a physiologically active APP fragment clumping into neurotoxic aggregates." (PMID 27120619, 2016). "As the gene for amyloid precursor protein (APP), which is one of the main players in the development of Alzheimer's disease (AD), is on chromosome 21, people with DS have a markedly increased risk of developing this disorder, making DS organoids valuable also for modeling AD." (PMID 27402594, 2016). "DHA stimulated non-amyloidogenic APP processing resulting in reduced Aβ levels in cellular models of Alzheimer's disease." (PMID 26074758, 2015). "By contrast, ‘sporadic’ Alzheimer's disease, which constitutes around 95% of cases, does not show any difference in the number of APP genes found in tissue samples, including whole brain." (PMID 25650802, 2015). "So far little is known about the impact of APP-dependent gene-regulation via AICD in MS, but pharmacological treatment studies in an animal model of Alzheimer ́s disease suggest that disruption of nuclear action of the AICD could improve neurological symptoms." (PMID 26426258, 2015). "The top-20 scoring GDAs from DisGeNET are very well-studied gene-disease relationships, like Alzheimer Disease and APP [amyloid beta (A4) precursor protein], obesity and MC4R (melanocortin 4 receptor), and Type 2 Diabetes Mellitus and IRS1 (insulin receptor substrate 1)." (PMID 25877637, 2015). "APP has been studied primarily in the context of Alzheimer's disease, but knowledge of other biological functions has not been as well studied." (PMID 25926793, 2015).
Alzheimer disease (continued). "Surprisingly, targeted exome sequencing of large multiplex pedigrees with LOAD identified mutations in APP, PSEN1, and PSEN2,11, 12 indicating that rare coding sequence variants even in genes associated with early onset Alzheimer disease (AD) may account for a portion of disease risk in LOAD." (PMID 26101835, 2015). "Soluble fragments of the amyloid precursor protein (APP) generated by α- and β-secretases, sAPPα and sAPPβ, have been postulated as promising new cerebrospinal fluid (CSF) biomarkers for the clinical diagnosis of Alzheimer’s disease (AD)." (PMID 25573162, 2015). "Recently we found that a non-canonical YXXØ-signal on the cytosolic tail of the Alzheimer's disease amyloid precursor protein (APP) binds to a distinct region of the μ4 subunit of the AP-4 complex." (PMID 24498434, 2014). "The significance of amyloid precursor protein (APP) and neuroinflammation in idiopathic normal pressure hydrocephalus (iNPH) and Alzheimer's disease (AD) is unknown." (PMID 24638077, 2014). "That uncertainty is magnified by uncertainty about the function of APP—despite years of research into the pathophysiology of Alzheimer's disease, there is still no clear understanding of what APP does outside the context of the disease." (PMID 23690749, 2013). "For this reason developers of pharmaceuticals for Alzheimer’s disease have expended enormous efforts to identify compounds that modify γ-secretase-mediated processing of APP without affecting the enzyme’s processing of Notch." (PMID 24023935, 2013). "Increased rate of neuronal apoptosis and amyloid precursor protein (APP) gene transactivation are also observed upon ETS2 over expression, which might play an important role in the early onset of Alzheimer’s disease and neuronal abnormalities in DS." (PMID 23343470, 2013). "Interestingly, this degeneration was associated with a diminished neuronal iron transport mediated by amyloid precursor protein (APP), the protein processed into the aggregation-prone β-amyloid (Aβ) in Alzheimer’s disease." (PMID 25258700, 2013). "While the presence of APP in this report probably reflects neuronal activity, increases in brain APP have also been correlated with increased GFAP in both Alzheimer’s disease and autism and these could also reflect glial activity." (PMID 23803181, 2013). "The present study identified LRP10 as a novel APP sorting receptor that protects APP from amyloidogenic processing, suggesting that a decrease in LRP10 function may contribute to the pathogenesis of Alzheimer’s disease." (PMID 22734645, 2012). "Our multi-compartment model represents a major conceptual advance over single-compartment models previously used to simulate APP processing; and it identified APP dimers and β-secretase as the two distinct targets of the inhibitory action of SORLA in Alzheimer’s disease." (PMID 22727043, 2012). "Our observations that USP25 interacted with APP and affected APP turnover implicate USP25 in Alzheimer's Disease pathogenesis and may serve as a point of intervention for new therapeutic strategies." (PMID 22590560, 2012). "Intramembranous γ-secretase cleavage of the amyloid precursor protein (APP) is the final step in the production of the amyloid-β peptide (Aβ); the main constituent of amyloid plaques found in the brains of patients with Alzheimer's disease." (PMID 21364883, 2011). "Furthermore, rapid intra-axonal amyloid-β accumulation was similarly observed post controlled cortical injury in APP/PS1 mice, another transgenic Alzheimer's disease mouse model." (PMID 21980472, 2011). "Missense mutations in three different genes encoding amyloid-β precursor protein (APP, [MIM 104760]), presenilin 1 (PSEN1, [MIM 104311]) and presenilin 2 (PSEN2, [MIM 600759]) are recognized to cause familial early-onset Alzheimer disease (EO-AD; [MIM 104300])." (PMID 22044463, 2011).